XAF1 (XIAP associated factor 1)
Description:
Seems to function as a negative regulator of members of the IAP (inhibitor of apoptosis protein) family. Inhibits anti-caspase activity of BIRC4. Induces cleavage and inactivation of BIRC4 independent of caspase activation. Mediates TNF-induced apoptosis and is involved in apoptosis in trophoblast cells. May inhibit BIRC4 indirectly by activating the mitochondrial apoptosis pathway. After translocation to mitochondria, promotes translocation of BAX to mitochondria and cytochrome c release from mitochondria. Seems to promote the redistribution of BIRC4 from the cytoplasm to the nucleus, probably independent of BIRC4 inactivation which seems to occur in the cytoplasm. The BIRC4-XAF1 complex mediates down-regulation of BIRC5/survivin; the process requires the E3 ligase activity of BIRC4. Seems to be involved in cellular sensitivity to the proapoptotic actions of TRAIL. May be a tumor suppressor by mediating apoptosis resistance of cancer cells.
Synonyms: BIRC4BP; XIAPAF1; HSXIAPAF1
Tractability: PROTAC: ubiquitination databases record sites on it.
Gene: Protein-coding gene on chromosome 17 (6,755,377 to 6,775,647, forward strand). Ensembl gene ENSG00000132530.
Subcellular location: Cytoplasm; Nucleus; Mitochondrion; Nucleus (Isoform 1); Nucleus (Isoform 5)
Subcellular location (Human Protein Atlas): Mitochondria; Nucleoplasm
Pathways (Reactome):
Immune System: Interferon alpha/beta signaling
Gene Ontology:
Molecular function: molecular sequestering activity; protein binding; zinc ion binding
Biological process: negative regulation of type I interferon production; response to interferon-beta; apoptotic process
Cellular component: mitochondrion; nucleoplasm; cytoplasm; cytosol; nucleus
Genetic constraint (gnomAD): Loss-of-function variants: 36 observed, 37.1 expected, observed/expected ratio (o/e) 0.97, 90% interval 0.74 to 1.28. The upper end of that interval is the gene's LOEUF score, 1.28, which puts it in group 5 of 6, group 1 being the genes least tolerant of losing a copy. Missense variants: 379 observed, 383.28 expected, observed/expected ratio (o/e) 0.99, 90% interval 0.91 to 1.08. Synonymous variants: 120 observed, 129.94 expected, observed/expected ratio (o/e) 0.92, 90% interval 0.8 to 1.08.
Homologues: Orthologues: chimpanzee XAF1 (98% identical), macaque XAF1 (91% identical), pig XAF1 (52% identical), rat Xaf1 (49% identical), guinea pig Xaf1 (49% identical), mouse Xaf1 (45% identical), dog XAF1 (38% identical), zebrafish xaf1 (25% identical). Paralogues in human: TRAFD1 (28% identical).
Diseases named in the same sentence as XAF1 in open-access papers:
XAF1 is named in the same sentence as 81 diseases in open-access papers, as found by Europe PMC text mining. Sharing a sentence is not in itself a finding about the gene and the disease. The quoted sentences say what the papers report.
COVID-19 (20 papers, 2021 to 2024). A disease caused by infection with severe acute respiratory syndrome coronavirus 2. "A single-cell transcriptomic study in peripheral blood mononuclear cells showed that COVID-19 caused XAF1-induced T lymphocyte apoptosis, leading to adaptive immune impairment." (PMID 35625619, 2022). "Additionally, T-cells in COVID-19 patients exhibited three distinct mechanisms of active apoptosis: the X-linked inhibitor of apoptosis (XIAP)-associated factor 1 (XAF1) pathway, the TNF pathway, and the Fas receptor pathway." (PMID 38542251, 2024). "Single-cell transcriptional analysis of peripheral blood mononuclear cells (PBMCs) in COVID-19 patients showed up-regulation of interferon stimulated genes (ISGs) in T, B, NK, and DC cell subsets, including X-linked inhibitor of apoptosis (XIAP)-associated factor 1 (XAF1)." (PMID 35244141, 2022). "We also identified IFN-stimulated, disease-specific genes; for example, XAF1 is specifically upregulated in COVID-19 patients while IFITM1 is specifically upregulated in HIV-1+ patients." (PMID 36992700, 2023). "Quantitative mRNA expression level demonstrated that XAF1 was selectively upregulated in COVID-19 FISH-positive kidneys compared with non–COVID-19 ATI injured kidney and hantavirus-infected kidneys, supporting its specific upregulation in SARS-CoV-2–infected kidneys." (PMID 36749641, 2023). "Our data and other clinical data sets have suggested that elevated XAF1 expression is positively correlated with the SARS-CoV, MERS-CoV, and SARS-CoV-2 infection in the lungs as well as the symptoms of the COVID-19 and influenza patients." (PMID 35972291, 2022). "Similarly, more XAF1 transcripts were detected in the PBMCs from the SARS-CoV-2-positive COVID-19 patients than the healthy controls." (PMID 35972291, 2022). "An additional 8 targets (CXCL6, IFI44, IFI44L, RSAD2, S100A8, SPRR2A, SYNE1, XAF1) are associated with COVID-19 pathogenesis, but do not have therapies targeting them available for potential repurposing." (PMID 34582497, 2021). "We also found the XAF1 gene was specifically upregulated in SARS-CoV-2–positive kidney biopsies compared with controls, SARS-CoV-2–negative COVID-19 kidneys, and Hantavirus-infected kidneys." (PMID 36749641, 2023). "Important gene combinations in the white blood cells of patients with COVID-19, including IFIT3, OASL, USP18, XAF1, IFI27, and EPSTI1, can be used for its diagnosis." (PMID 35928229, 2022). "The optimal 24 feature genes, which were further analyzed by consulting the retrieved literature, we found that four genes (XAF1, OAS2, CES1, RPS8) have been reported in COVID-19." (PMID 35812523, 2022). "In addition, IPIN analysis from COVID-19 patient lung tissue revealed that IFIH1, DDX58, ISG15, OASL, and XAF1 were hub genes in the network." (PMID 35625619, 2022). "Unlike the other five hub genes, the significant expression of XAF1 has a negative impact on the human body and may become a therapeutic target for COVID-19." (PMID 34920753, 2021).
colon carcinoma (15 papers, 2008 to 2025). "The X-linked IAP (XIAP), a member of IAP, and XIAP-associated factor 1 (XAF1) were examined in colon cancer cells stimulated with decitabine along with gefitinib." (PMID 24874286, 2014). "An INF-stimulated gene, XIAP-associated factor 1 (XAF1), which was induced by RA in colon cancers resulted in growth suppression." (PMID 19088887, 2008). "The protein known as the X-linked inhibitor of apoptosis (XIAP)-associated factor 1 (XAF1) is a tumor-suppressor gene expressed in many types of tumor cells, including lung adenocarcinoma and colon tumor cells." (PMID 37569299, 2023). "Enhancement of XAF1 expression by IFNβ and subsequent apoptosis via the IFNβ-XAF1 pathway has been reported in a colon cancer cell line and in germ cells." (PMID 35829914, 2022). "DHM can activate phosphorylation of AMPK and upregulate XIAP-associated factor 1 (XAF1) through ROS-mediated ER stress; subsequently, it upregulates XAF1 and disrupts mitochondrial membrane potential, leading to apoptotic death in colon cancer." (PMID 35884547, 2022). "XAF1 expression is downregulated in a variety of tumor cells including gastric and colon cancer cell lines, and transient expression of XAF1 sensitizes tumor cells to the pro-apoptotic effects of some anti-tumor drugs 14, 17, 19-21." (PMID 35517406, 2022). "XAF1 is also implicated as a tumor suppressor and is down-regulated in a variety of tumor cells including gastric and colon cancer cells, and overexpression of XAF1 sensitizes tumor cells to the pro-apoptotic effects of some anti-tumor drugs 14, 17, 19-21." (PMID 35517406, 2022). "Previously, it has been reported that in colon cancer, XAF1 expression is upregulated after inhibition of the MAPK pathway through transcriptional regulation, which mediated apoptosis." (PMID 33734579, 2021). "We found that depletion of XAF1 by siRNA attenuated apoptosis of colon cancer cell induced by decitabine in combination with gefitinib." (PMID 24874286, 2014). "Our findings suggested that gefitinib in combination with decitabine exerted enhanced cell apoptosis in colon cancer cells were involved in mitochondrial-mediated pathway and induction of XAF1 expression." (PMID 24874286, 2014). "More importantly, the expression of both mRNA and protein levels of XAF1 was remarkably increased in colon cancer cells treated by using two drugs in combination compared to single agent treatment." (PMID 24874286, 2014). "Gene therapy for recombinant adenovirus vector mediated XAF1 significantly suppressed tumor growth in gastric and colon cancer in vitro and in vivo." (PMID 24980821, 2014). "Our previous studies have shown that XAF1 induced apoptosis through intrinsic and extrinsic apoptosis pathways in gastric and colon cancer cells." (PMID 24980821, 2014). "Together, these findings suggested that XAF1 contributed to the sensitivity of colon cancer cells to apoptotic induction after combined treatment with gefitinib and decitabine." (PMID 24874286, 2014). "Knockdown of XAF1 significantly attenuated cell apoptosis induced by gefitinib treatment in combination with decitabine in colon cancer cells." (PMID 24874286, 2014). "Interestingly, other studies have found that overexpression of XAF1 can inhibit the tumor cell growth of lung cancer, liver cancer, and colon cancer through the induction of apoptosis and an increase in the sensitivity to radiotherapy and chemotherapy." (PMID 33879231, 2021). "Our results suggest that Ad5/F35-XAF1 induces apoptosis of liver cancer cells through both endogenous and exogenous pathways, supporting our previous reports that XAF1 induces apoptosis in gastric and colon cancer cells." (PMID 24980821, 2014).
colon carcinoma (continued). "Moreover, small interfering RNA (siRNA) depletion of XAF1 significantly attenuated colon cancer cells apoptosis induced by the combination of the two drugs." (PMID 24874286, 2014). "Moreover, our study results suggested that mitochondria-mediated and XAF1-dependent apoptotic pathways were involved in decitabine plus gefitinib-induced cell death in colon cancer cells." (PMID 24874286, 2014). "Moreover, in many colon cancers, the CpG island of XAF1 gene is hypermethylated, resulting in transcriptional repression." (PMID 24874286, 2014). "Notably, the expression of XAF1 was upregulated modestly by gefitinib alone in colon cancer cells, raising another likely explanation for the upregulation of XAF1 was that gefitinib also targeted epigenetic pathways." (PMID 24874286, 2014). "We then asked if the two drugs in combination could enhance XAF1 mRNA levels in colon cancer cells." (PMID 24874286, 2014). "We selected eight representative immune-related molecules for qPCR validation in SW480 and another colon cancer cell line HT29: DDX58, CHST4, TNFSF18, XAF1, OAS1, IFI27, IFI44, IFIT3." (PMID 38281029, 2024). "DDX58, XAF1, OAS1, IFI27, IFI44 or IFIT3 was indeed downregulated and CHST4 or TNFSF18 was upregulated in MDM4 overexpressed colon cancer cells." (PMID 38281029, 2024). "In the case of human colon cancer cells, exposure to TGF-β1 in vitro resulted in the protection of these cells from apoptosis by a mechanism involving the activation of ERK 1/2 and the repression of transcription of XAF1." (PMID 37569299, 2023).
melanoma (14 papers, 2006 to 2024). A malignant, usually aggressive tumor composed of atypical, neoplastic melanocytes. "In the TCGA melanoma tumors, we observed a predominant full‐length XAF1 expression, and presence of all transcripts was associated with better overall survival." (PMID 33734579, 2021). "For example, TRAIL and XIAP associated factor 1(XAF1) are believed to contribute to IFN-induced apoptosis in melanoma cells, whereas an induction of the regulators of IFN-induced death (RIDs) is necessary in IFN-induced ovarian carcinoma cell apoptosis." (PMID 26452032, 2015). "The induction of XAF1 by IFN-β in human melanoma cell lines results in enhanced susceptibility to TRAIL-induced apoptosis." (PMID 17376236, 2007). "Loss of heterozygosity of XAF1 gene has been reported in human colorectal cancers and promoter CpG hypermethylation of XAF1 has been found in several human malignant tumors such as gastric, colon, melanoma and urogenital tumor." (PMID 24980821, 2014). "We observed a strong correlation between MX2 and XAF1 in the primary melanomas, while in metastatic tumors from this correlation was weaker, although still significant." (PMID 33734579, 2021). "MX2 and XAF1 expression tightly correlate in both cultured melanoma cell lines and in patient‐derived primary and metastatic tumors, where they also are significantly related with survival." (PMID 33734579, 2021). "While MX2 overexpression renders melanoma cells less proliferative, previously, it has been shown that activation of the IFN pathway and higher XAF1 expression are associated with increased cell sensitivity to cytotoxic treatments." (PMID 33734579, 2021). "Higher MX2 expression renders melanoma cells more sensitive to targeted therapy drugs such as vemurafenib and trametinib; however, this effect is XAF1 independent." (PMID 33734579, 2021). "We also examined XAF1 mRNA and protein expression in melanocytes and melanoma cell line panel previously investigated for MX2 expression." (PMID 33734579, 2021). "We first checked the distribution of XAF1 isoforms in the TCGA melanoma samples using the GEPIA2 analysis tool." (PMID 33734579, 2021). "We detected relatively low XAF1 RNA levels in normal human melanocytes, while they were significantly higher in two primary and four metastatic melanoma lines." (PMID 33734579, 2021). "We also show that MX2 mediates IFN inhibitory effects in melanoma, sensitizes melanoma cells to MAPK pathway targeted therapy, and regulates XAF1 that has prognostic impact in melanoma patients." (PMID 33734579, 2021). "We first tested the effects of XAF1 siRNA knockdown on the proliferation of XAF1 expressing melanoma cells over a 72 h period using Incucyte system." (PMID 33734579, 2021). "The tumor suppressor role of XAF1 is well established in several gastrointestinal cancers, melanoma, and urogenital cancers, where its expression levels are documented to be extremely low23–29." (PMID 31575897, 2019). "Firstly, a panel of neuroblastoma and neural crest-derived melanoma cell lines were screened for XAF1 basal expression including SK-N-AS and SK-N-SH neuroblastoma cells." (PMID 27097110, 2016). "XAF1 levels are drastically decreased in a significant number of cancer cell lines, as well as in a collection of gastric cancers, melanoma specimens and urogenital cancers." (PMID 17376236, 2007). "A previous study has shown that overexpression of xaf1 promotes TRAIL-induced apoptosis in melanoma cells." (PMID 17376236, 2007). "Juraleviciute and their colleagues noticed that the MX2 could regulate the XAF1 and make the melanoma cells sensitive to targeted therapy." (PMID 37063301, 2023). "Our immunoblotting data of melanoma cell lines show that the XAF1 antibody detects two separate bands with both being downregulated after the addition of the XAF1 siRNA, suggesting that different XAF1 isoforms may be present in these cell lines." (PMID 33734579, 2021).
melanoma (continued). "Reduced protein levels of XAF1 have been reported in primary melanoma tumors compared to nevi." (PMID 33734579, 2021). "Since we here have identified XAF1 as an effector downstream of MX2, and XAF1 has previously been shown to inhibit tumor growth and mediate apoptotic effects in several cancers, we asked if XAF1 can have a similar function in melanoma cells." (PMID 33734579, 2021). "Collectively, our data suggest that XAF1 might be partially mediating MX2 growth effects in melanoma tumors as well." (PMID 33734579, 2021). "Moreover, XAF1 was previously shown to be involved in mouse neuronal developmental apoptosis and cancers with neural crest origin such as melanoma and neuroblastoma." (PMID 27097110, 2016). "In addition, MX2 may also modulate XAF1 to increase the sensitivity of melanoma cells to targeted therapies, which may be related to immune responses." (PMID 36059547, 2022). "It has been reported that XAF1 exists in several isoforms and that the full‐length transcript (XAF1A) is often inactivated in several tumors types, including melanoma." (PMID 33734579, 2021). "Our RNA‐seq analysis revealed XAF1 as one of the top candidate genes induced by MX2 overexpression, which was also observed in several other melanoma cell lines and primary human melanocytes engineered to overexpress MX2." (PMID 33734579, 2021). "Studies also showed that loss or reduction of XAF1 expression without any corresponding inactivating mutation or deletion, is frequently associated with malignant tumor progression in a variety of cancers including melanoma, gastric, colon and pancreatic cancers." (PMID 27097110, 2016). "More recently, XAF1 was demonstrated to be critical in overcoming resistance to apoptosis induction by IFN-β in renal carcinoma and melanoma cells." (PMID 17376236, 2007). "Interestingly, we showed that in melanoma cells, MX2 mediates growth‐inhibitory effects of IFNα in a highly cell‐specific manner either via XAF1 or XAF1 independently." (PMID 33734579, 2021). "Furthermore, we performed XAF1 knockdown in additional BRAF and NRAS mutant melanoma cultures (Figure [Link], [Link]) and observed the same trend." (PMID 33734579, 2021). "Moreover, we have previously demonstrated that MX2 overexpression suppresses growth of melanoma cells and tumors partially by reducing the AKT pathway activity 5 and results presented here suggest that XAF1 contributes to this regulation." (PMID 33734579, 2021). "Furthermore, the expression of proapototic protein XAF1, which blocks the XIAP-mediated inhibition of caspase-3, is also reduced in human melanomas." (PMID 16755297, 2006). "Moreover, XAF1 overexpression was also able to induce apoptosis to a similar or greater extent than KIF1Bβ alone in NB1 neuroblastoma cells and neural crest-derived SK-MEL-28 melanoma cells." (PMID 27097110, 2016). "We saw that XAF1 knockdown increased proliferation of NRAS, but not BRAF mutant melanoma cells, yet we acknowledge that this effect was observed in a limited number of cell lines." (PMID 33734579, 2021). "However, even though we did observe an upregulation of XAF1 following MAPK pathway inhibition in melanoma cells, XAF1 downregulation did not affect responses to the drugs indicating that MX2 sensitization is achieved independent of XAF1." (PMID 33734579, 2021).